TFF3 (trefoil factor 3)
Diseases named in the same sentence as TFF3 in open-access papers (continued):
Sharing a sentence is not in itself a finding about the gene and the disease.
tumor (continued). "Besides, TFF3 expression correlates with the tumor grade in hepatocellular carcinoma, is highly expressed in intestinal metaplasia, and a marker for poor prognosis in gastric carcinoma." (PMID 27626280, 2016). "Knowledge of the expression of oestrogen-responsive biomarkers could assist in treatment stratification, because tumours that express TFF3, TFF1 and progesterone receptor are more likely to respond." (PMID 25900183, 2015). "Hence, forced expression of TFF3 in MCF-7 cells increased tumor microvessel density and subsequently promoted angiogenesis in vivo." (PMID 26559818, 2015). "In addition, tumour expression of TFF3 mRNA predicts a worse survival outcome in ER+ patients treated with tamoxifen and increased expression of TFF3 both reduces sensitivity of ER+ MC cells to tamoxifen and mediates acquired resistance to tamoxifen." (PMID 25266665, 2014). "Our data indicate that TFF3 may be an effective biomarker of tumor stage and the presence of distant metastasis, and may be a pharmacodynamic marker of response to chemotherapy in gastrointestinal cancer." (PMID 25031551, 2014). "Among ER- and PR- tumours, 58% (44 out of 75 cases) tumours are TFF3 positive." (PMID 25266665, 2014). "Similarly, we herein and others have also reported that TFF3 expression in the primary tumour predicted lymph node metastasis of MC." (PMID 25266665, 2014). "In contrast, all tumours positive for TFF3 expression were also positive for pSTAT3." (PMID 25266665, 2014). "(This may account for the paradoxical changes seen in the TFF3 found in tumour #59, which were increased in expression at both 14 days and three months)." (PMID 20646288, 2010). "Tumour tissues showed markedly increased TFF3 positivity as compared with normal tissues (P<0.01)." (PMID 18682706, 2008). "Indeed, even at this lower CA125 setting, TFF3 remained a more sensitive indicator of tumour presence than CA125." (PMID 18682706, 2008). "Some studies showed that immunoreactive TFF3 expression has been detected in neoplastic human colonic mucosa, colocalising with neutral mucin production, but loss of TFF expression is associated with tumour necrosis and advanced Dukes' stage." (PMID 15083192, 2004). "In addition, GATA3, ERBB4, RET, NAT, and TFF3 genes are commonly expressed in tumor cells, which may also influence response to treatment." (PMID 36536751, 2022). "Notably, the hypoxia/glycolysis signature contains intestinal differentiation markers (e.g., TFF3, FABP1, KRT19), indicating an association of distinct metabolic states with tumor cell differentiation and proliferation, as recently described for the normal intestinal crypt." (PMID 33806447, 2021). "Furthermore, we used a tail vein injection assay to investigate whether the metastatic ability of tumor cells is influenced by TFF3 in vivo." (PMID 34262017, 2021). "However, other reports indicate that TFF3 may function as an oncogene or as a tumor suppressor depending on the cellular context." (PMID 28930171, 2017). "Herein, we demonstrated that forced expression of Trefoil factor 3 (TFF3), in oestrogen receptor-positive (ER+) EC cells significantly increased cell cycle progression, cell survival, anchorage-independent growth, invasiveness and tumour growth in xenograft models." (PMID 29100386, 2017). "Thus, TFF3 may serve oncogenic or tumor suppressive functions depending on cell type and disease stage in at least some malignancies." (PMID 28930171, 2017). "Moreover, it was reported that TFF3 expression in tumour cells disseminated to lymph nodes was significantly higher than that observed in the primary tumour and further significantly enhanced in tumour cells that penetrated the node capsule." (PMID 25266665, 2014). "BL tumor cells exhibited elevated expression of MGP (matrix Gla protein), AZGP1 (alpha-2-glycoprotein 1), AGR2 (anterior gradient protein 2), TFF3 (trefoil factor 3), and FGFR1 compared to EP and LP cells." (PMID 39955556, 2025).
tumor (continued). "Conversely, other genes were highly expressed and broadly distributed in PCa sections, with TFF3 and TSPAN1 concentrated in tumor regions." (PMID 40161494, 2025). "In Cluster 10 (DCIS/LCIS), upregulated genes such as CPB1, COX6C, TFF3, and IL6ST reflect early-stage tumor characteristics and immune regulation." (PMID 41182757, 2025). "Mechanistically, the samples suppressed tumor growth via apoptosis regulation; restored epithelial integrity by modulating MUC-2, MUC-3, and TFF-3 expression; and attenuated inflammatory cytokine expression through NF-κB pathway modulation." (PMID 41154100, 2025). "The results showed that the expression of IPCEF1, TFF3, GLT8D2, TPO and DIO1 were downregulated in the tumor group and DPP4, LRP4, CDH3, KCNJ2, CLDN1, GABRB2, FN1 were upregulated in the tumor group." (PMID 39513122, 2024). "TFF3 and VEGF can promote tumor cells to enter the circulation system by the high vascular permeability, and then ended with their seeding and growing in a remote site." (PMID 38773485, 2024). "Serum vascular endothelial growth factor (VEGF) and trefoil factor 3 (TFF3) can promote the growth of blood vessels, which are conducive to the tumor proliferation and spreading." (PMID 38773485, 2024). "DEG analyses revealed the genes contributing to RFS and related to SUVmax (PSG5, TFF3, SOX2, SLC5A5, and SLC5A7) and tumor size (HOXD10, IFNA1, and FER1L6)." (PMID 38745021, 2024). "Subcluster 5, distinctly derived from the tumour tissue, overexpressed mucus secretion‐related genes (CXCL17, TFF3, MUC5AC, SPINK4 and MSMB, etc.)." (PMID 35075805, 2022). "Reduces tumor weight, increases the levels of IFN-γ, TNF-α, GZMB and the expression of CLCA3, TFF3, AGR2, Zg16, Pla2g10, Guca2a." (PMID 35548468, 2022). "Exploration of the expression network indicated that inflammatory genes (CXCL8, CXCL3, PIGR, and RNASE1) and Wnt pathway genes (GAST, REG1A, TFF3, and ZG16B) are upregulated in tumor stem cells of UGICs." (PMID 35646860, 2022). "Pharmacological inhibition of TFF3 by AMPC, resulted in markedly decreased cell survival, proliferation, 3D growth and foci formation, and impaired tumor growth in a xenograft mouse model." (PMID 31685806, 2019). "Herein, we provided functional and mechanistic evidence that TFF3 promotes tumor progression in lung ADC, following the previous observation of highly specific TFF3 expression in lung ADC19." (PMID 31685806, 2019). "Over-expression of TFF3 was found in HCC tissues and positively correlated with tumor size and stage." (PMID 30424721, 2018). "The epithelial cell cluster unique to patient HG3 from this tumor had eleven differentially expressed genes with highest expression found in SST, TFF3 and PIGR." (PMID 30383866, 2018). "In order to assess the clinical relevance of TFF3 expression in HCC patients, we analyzed the expression levels of TFF3 protein in adjacent non-tumor liver specimens (n=110) and HCC specimens (n=138) using immunohistochemistry (IHC)." (PMID 28445151, 2017). "Higher expression levels of TFF3 protein were observed in HCC specimens, while lower expression levels were detected in the adjacent non-tumor specimens." (PMID 28445151, 2017). "PTC and FTC tumours presented a group of common dysregulated proteins including SOD3, ISLR, biotinidase, polymerase I and transcript release factor (cavin-1), TFF3, alpha(B)-crystallin (CryAB), AGR2, tenascin and 14-3-3 gamma." (PMID 27025787, 2016). "Conversely, a reduction in TFF3 (or an increase in IGFBP5) following tamoxifen treatment in vivo and the protein levels in primary tumors correlated with a reduction in tumor volume in the 28 patients treated with tamoxifen for three months." (PMID 20569502, 2010). "Several immune scoring metrics, including IFN-γ, methylation-based tumor-infiltrating lymphocytes (MeTIL), T cell inflamed, and cytolytic activity (CYT) scores, show a strong correlation between elevated TFF3 expression, reduced IFN-γ, and lower immune infiltration levels." (PMID 41551914, 2026).
tumor (continued). "Notably, genes such as TFF3, CLDN3, CDH17, and REG4 exhibited specific expression in tumor cells, linking to the cancer progression." (PMID 40452847, 2025). "Comprehensive profiling of nearly 80 CRC-derived cell lines and direct tumor specimens has led to the classification of CRCs into five distinct subgroups based on MUC2 and TFF3 expression, ranging from nearly normal goblet cell differentiation to complete absence." (PMID 41002393, 2025). "After that, we re-subtypeed tumor cells, and annotated them according to each cell marker gene, and identified six tumor cell subtypes: C0 XIST+ tumor cells, C1 SCGB2A1+ tumor cells, C2 IGF2+ tumor cells, C3 UBE2C+ tumor cells, C4 TFF3+ tumor cells and C5 IGFBP3+ tumor cells." (PMID 39896800, 2024). "Similarly, multiple studies have shown that TFF3 and NELL2 are significantly upregulated in tumor tissue compared to adjacent normal tissue, promoting tumor migration, growth, and leading to poor prognosis." (PMID 38277205, 2024). "Based on marker genes for every cluster, we revealed one set of lymphatic endothelial cells (cluster 9, TFF3 +) and nine sets of vascular endothelial cells (FLT1 +): One was mostly interface-derived (clusters 2; HLA-DQA2 +) and three were mostly tumor-derived (clusters 4, 6 and 8; ROBO1 +)." (PMID 37644609, 2023). "Two genes, TFF3 and FCGBP, were downregulated in Xenopus tumor and upregulated in human cancer." (PMID 37580380, 2023). "Bioinformatic study showed that tumor stem cells activated TCF3, SMARCA4, TFF3, etc.." (PMID 37717019, 2023). "Upregulated hPG80 and TFF3 induce PI3K/Ras and lead to tumor cell growth and invasion, which may be one reason for the poor prognosis of UGIC." (PMID 35646860, 2022). "The sub‐clustering of ECs revealed six subtypes, including extra‐alveolar capillary EC (cEC) (FCN3+EDN1+PLVAP+), alveolar cEC (HPGD+EDNRB+IL1RL1+), arterial EC(GJA5+FBLN5+DKK2), lymphatic EC (CCL21+TFF3+FABP4), INSR+ tumour EC (INSRhiHSPG2+PLVAP+), and ACKR1+ tumour EC (ACKR1+SELP+IL1R1+)." (PMID 35184398, 2022). "The TFF3 level is commonly found in HCC patients and correlates with tumor grade." (PMID 34146542, 2021). "TFF3 has been studied as a promoter of EMT and tumor invasion in PTC." (PMID 34805166, 2021). "In order to show the tumor inductive potential of EMP1 in RB cells, we additionally overexpressed EMP1 in Y79 cells expecting to see the opposite effects following TFF3 overexpression, namely higher cell viability and proliferation levels as well as decreased cell death levels." (PMID 31450568, 2019). "Even the TFF3-negative tumor tissues showed a relatively higher IS (44.9% for IS 1–3 and 55.1% for IS 0) than did the normal tissues (13.6% for IS 1–3 and 86.4% for IS 0)." (PMID 30139961, 2018). "Functionally, forced expression of TFF3 in HCC cell lines increased cell proliferation, cell survival, anchorage-independent and 3D matrigel growth, cell invasion and migration, and in vivo tumor growth." (PMID 28445151, 2017). "The other two Trefoil factors are not considered tumor suppressors, even if lack of TFF2 seems to be predisposal to gastric malignancies and TFF3 is strongly up-regulated in intestinal metaplasia and therefore considered a marker of poor prognosis." (PMID 29085807, 2017). "A much weaker reaction was detected in tumours with low TFF3 mRNA concentrations (tumours 2 and 8), and there was no reaction in tumours in which TFF3 mRNA was undetectable." (PMID 25900183, 2015). "The absence of progesterone receptor, TFF1 and especially TFF3 expression in patients with oestrogen receptor-positive tumours provides a strong indication that patients will not benefit from hormonal therapy." (PMID 25900183, 2015). "For instance, there was high expression of oestrogen receptor but not TFF3 mRNA in tumours 2 and 7 and high expression of TFF3 but not oestrogen receptor mRNA in tumour." (PMID 25900183, 2015).
tumor (continued). "Amongst the oestrogen receptor-positive, TFF3-positive tumours, 84% responded and 68% had a partial or complete response, whereas only 37% of oestrogen receptor-positive, TFF3-negative tumours responded and none had a partial or complete response." (PMID 25900183, 2015). "TFF3 expression was higher in oestrogen receptor-positive tumours (Allred ≥3.0) than it was in oestrogen receptor-negative tumours (Mann–Whitney U test, P=0.000)." (PMID 25900183, 2015). "TFF3 was higher in progesterone receptor-positive tumours as compared to progesterone receptor-negative tumours (Mann–Whitney U test, P=0.001) and in TFF1-positive tumours as compared to TFF1-negative tumours (Mann–Whitney U test, P=0.000)." (PMID 25900183, 2015). "The amount of TFF3 mRNA varied enormously; there were high levels in ten, moderate levels in two, low levels in four and none in two tumours." (PMID 25900183, 2015). "The serum TFF3 level was did not significantly correlated with patient gender or age, the site of the tumor (fundus/cardia, body or antrum) or the degree of differentiation (well, moderately or poorly differentiated)." (PMID 25031551, 2014). "The serum TFF3 level was not significantly correlated with a patient’s tumor site or degree of differentiation." (PMID 25031551, 2014). "Whether the combined expression of NPM, TFF3 and TACC1 contributes a growth advantage of tumour must be further determined by in vitro and clinical studies." (PMID 24358147, 2013). "In conclusion, TFF3 and TACC1 over-expression in tumor epithelial cells of surgically resected gastic adenocarcinoma could independently predict a shorter survival." (PMID 24358147, 2013). "TFF3 was expressed in the cytoplasm of tumor epithelial cells (positive 44% vs. 56% negative), and no staining was observed in the nucleus (Figure." (PMID 24358147, 2013). "Because CA125 and TFF3 levels were not significantly correlated either in tumour patients or in negative controls, a combination of the two markers was analysed." (PMID 18682706, 2008). "Whether in tumor or non-tumor cells, TFF3 consistently exhibited upregulation in BL samples from patients who responded well to CDK4/6is." (PMID 39955556, 2025). "Finally, the evaluation of ERG, TFF3, and SPINK1 could be an attractive approach to determine both tumor heterogeneity and PCa subtypes." (PMID 38256434, 2024). "However, lymph-nodal involvement was observed in all cases in both groups, confirming the specific role of TFF3 in tumor cell spreading via blood vessels rather than via lymphatic system." (PMID 35216615, 2022). "Notably, TFF3 expression level correlates with the malignancy of tumor that scored by tumor grade not correlated with patient age, sex, tumor size, tumor location, severity of edema, or presence of cystic change (P>0.05 each)." (PMID 29100347, 2017). "Furthermore, the absence of TFF3 expression in tumours that express oestrogen receptor indicates that endocrine therapy is less likely to be effective." (PMID 25900183, 2015). "In addition to IL-8, it was noted that TFF3 modulated the expression of a number of other genes involved in angiogenesis, including TGF-β, and it is likely that the effect of TFF3 on tumor angiogenesis is the result of a co-ordinated and combinatorial pattern of gene expression." (PMID 26559818, 2015). "Of those tumours negative for TFF3 expression, 23.8% were positive for pSTAT3." (PMID 25266665, 2014). "After TFF3 depletion, the expression of M2 markers (CD163, CD206, ARG-1, and IL-10) and S100A4 and S100A8 were remarkably downregulated, which confirmed our hypotheses that iCCA cells induce the M2 phenotype and pro-tumor polarization of resident macrophages by secreting TFF proteins." (PMID 39256888, 2024). "However, a functional role for TFF3 in tumor angiogenesis has not been determined." (PMID 26559818, 2015).
tumor (continued). "To mitigate this, we classified normal TFCs using 3 additional markers (i.e., TFF3, TPO, SLC26A4) that were previously shown to be expressed in normal thyroids but not in tumor cells." (PMID 37053016, 2023). "In the study presented, we did not detect any effects of forced TFF3 expression on the migration potential of RBL-15 cells, derived from a bilateral tumor." (PMID 27626280, 2016). "Interestingly, genes such as TFF3, MGP, and IGKC were identified across all BL responder tumor cells, irrespective of metastatic site or tissue-specific signatures." (PMID 39955556, 2025).